FOXC1 (forkhead box C1)
Diseases named in the same sentence as FOXC1 in open-access papers (continued):
Sharing a sentence is not in itself a finding about the gene and the disease.
breast carcinoma (continued). "All results indicated that FOXC1 regulated expression of ERα and affected sensitivity of tamoxifen treatment in breast cancer, and that FOXC1 may be used as a new therapeutic target in ERα‐negative breast cancer." (PMID 28028927, 2017). "However, FOXC1 overexpression was not significantly correlated with breast cancer-specific OS in this patient group (P = 0.116)." (PMID 28493031, 2017). "Although previous studies have revealed many potential biomarkers associated with poor prognosis in basal-like breast cancer, including basal cytokeratins (CK5/6, CK14, CK17), epidermal growth factor receptor (EGFR), c-kit, P63, P-cadherin and FOXC1, currently, there are no targeted treatments." (PMID 27322681, 2016). "This may explain why M219 FOXC1 cells are more resistant to PLX4032 than M219 control and further confirmed previous similar results that Ron receptor tyrosine kinase activation confers resistance to tamoxifen in breast cancer cells." (PMID 27533251, 2016). "This analysis confirms previous findings that FOXC1 and GATA3 are involved in a switch between basal-like and luminal-like expression programs in breast cancer, and indicates that the high-resolution time-series data may identify novel factors that underlie this switch." (PMID 27539783, 2016). "Whether NR2F2 and FOXC1 influence their respective binding in TNBC remains to be determined, but the possibility of using the NR2F2-inhibitor to disrupt the interaction with FOXC1 in TNBC presents a potential targeted-therapy approach for basal-like breast cancer." (PMID 39171293, 2024). "Furthermore, protein levels corresponding to FOXC1 target genes were lower in Luminal B patients with high EZH2 and low FOXC1 expression, supporting our hypothesis that a FOXC1-driven transcriptional program is suppressed by EZH2 specifically in Luminal B breast cancer." (PMID 29959321, 2018). "Because of the critical role of FOXC1 in BLBC cell function, along with an opposing expression pattern between BRCA1- and BRCA2-mutant breast cancers, it is speculated that BRCA1, not BRCA2, mutation-elicited signaling might synergize with FOXC1 action in mammary tumorigenesis." (PMID 27708239, 2016). "Here we report aberrant methylation levels of ABCB1, FOXC1, GSTP1, PPP2R2B and RASSF1A in DCIS and stage I-IV providing evidence that suggests that changes in methylation level is an early event and may also be important in progression to later stages of breast cancer." (PMID 24093668, 2013). "Unlike FOXC1 and MET, the functional role of ANLN in breast cancer has not been studied extensively." (PMID 33854062, 2021).
glaucoma (62 papers, 2007 to 2025). Increased pressure in the eyeball due to obstruction of the outflow of aqueous humor. "FOXC1 variants have been identified in patients with childhood glaucoma associated with Axenfeld–Rieger anomaly, Peters anomaly and aniridia." (PMID 41011222, 2025). "It has been established that variations in FOXC1 gene are often associated with a wide range of abnormalities such as various types of glaucoma and systemic anomalies, including hearing loss." (PMID 38755526, 2024). "It should be noted that, compared to other mutations, ARS caused by FOXC1 remarkably promotes congenital glaucoma development." (PMID 39407821, 2024). "In humans, an association of the forkhead box C1 transcription factor (FOXC1) gene with Axenfeld–Reiger syndrome has been identified, which also includes glaucoma in some individuals." (PMID 38255979, 2024). "In about 40% of patients with Axenfeld–Rieger anomaly (ARA), which is associated with glaucoma in 50 to 75%, either FOXC1 or PITX2 mutations are found." (PMID 35011756, 2021). "Generally, children with FOXC1 variants are prone to developing into glaucoma and other ocular disorder, which underline the necessity of definite diagnosis by genetic methods along with subsequent early prevention of ocular defects." (PMID 34809627, 2021). "We unravel by WES a novel mutation in FOXC1 behind the ocular basic phenotype, and we propose a digenic model for the glaucoma phenotype along a mutation in the DPT gene and another digenic model for CHD involving yet a novel mutation in NFATC1." (PMID 28979898, 2017). "Alterations in FOXC1 levels cause ocular malformations and disrupt stress response in ocular tissues, thereby contributing to glaucoma progression." (PMID 28575017, 2017). "Mutations in the transcription factor FOXC1 can cause Axenfeld-Rieger syndrome, a disorder of abnormal eye and tooth development that frequently involves glaucoma." (PMID 28210622, 2017). "We propose a digenic model for glaucoma in this family by combining the FOXC1 variant with a missense variant inherited from the father in the dermatopontin (DPT) gene." (PMID 28979898, 2017). "MYOC is a protein associated with early onset glaucoma, similarly to FOXC1, and is also involved in steroid induced glaucoma." (PMID 28575017, 2017). "FOXC1 is known to play a critical role in embryonic ocular and brain development, with mutations or deletions resulting in glaucoma-related ocular dysgenesis and Dandy-Walker malformations." (PMID 27708239, 2016). "Mutations in FOXC1 have previously been described in patients with Axenfeld-Rieger anomaly and/or glaucoma (OMIM*601090)." (PMID 27000031, 2016). "Human FOXC1 heterozygous mutations are well known to affect eye development, causing a spectrum of ocular-associated anomalies including glaucoma and Axenfeld-Rieger syndrome." (PMID 27103944, 2016). "The glaucoma feature appeared to be present in 26% of individuals with a molecular diagnosis (particularly in FOXC1 and PITX2 mutation-positive patients) compared to 7% of those without a diagnosis." (PMID 27124303, 2016). "It has been shown that patients diagnosed with Axenfeld-Rieger malformation who carry FOXC1 duplications have a more severe prognosis for glaucoma development than patients with FOXC1 mutations." (PMID 25786029, 2015). "In summary, this study shows that FOXC1 sequence variations with moderate activity defects are associated with dominant glaucoma and remarkable phenotypic variability." (PMID 25786029, 2015). "The FOXC1 mutation is more likely to be associated with glaucoma, while the risk of systemic abnormalities is greatest with the PITX2 mutation." (PMID 23687430, 2013). "There is a previous report of gross lack of iris and concurrent keratopathy associated with heterozygous FOXC1 mutation; this was in a baby boy who also had severe newborn glaucoma." (PMID 21423868, 2011).
glaucoma (continued). "Patients with FOXC1 mutations have a milder average prognosis for glaucoma development than do patients with any one of the known PITX2 mutations." (PMID 22022403, 2011). "The gene FOXO1 belongs to the forkhead family of transcription factors, the same family as the candidate gene FOXC1 (6q25) that was previously associated with early onset glaucoma (see Introduction)." (PMID 20485516, 2010). "Haploinsufficiency through mutation or deletion of the forkhead transcription factor, FOXC1, causes Axenfeld-Rieger anomaly, which manifests as a range of anterior segment eye defects and glaucoma." (PMID 19626132, 2009). "Additionally, recent research indicates that mutations in FOXC1 are associated with a greater extent of corneal abnormalities and a higher frequency of glaucoma compared to mutations in PITX2." (PMID 39407821, 2024). "It has been shown that FOXC1 variants are a common cause of Swiss childhood glaucoma." (PMID 35663518, 2022). "These transcription factors are involved in regulating embryonic and ocular development, and FOXC1 mutations are associated with various glaucoma phenotypes, including primary congenital glaucoma and Axenfeld–Rieger syndrome, which characterized by specific ocular anomalies." (PMID 35464367, 2022). "Interestingly, FOXC1-associated glaucoma generally has an earlier onset than PITX2 related ARA, but glaucoma in PITX2 patients seems to be more severe and more difficult to treat." (PMID 35011756, 2021). "Loss of Foxc1 function in zebrafish also leads to endophenotypes of glaucoma, including reduced number of retinal ganglion cells and thinner optic nerves, providing a valuable model to study the increased glaucoma risk associated with ARS." (PMID 34576164, 2021). "FOXC1 gene variations identified in dominant glaucoma cases and associated clinical features." (PMID 25786029, 2015). "On the converse, FOXC1 is a gene that regulates the development of the anterior segment of the eye, and it is known to be involved in several autosomal dominant eye defects associated with an increased risk for glaucoma." (PMID 25786029, 2015). "Cytochrome P450, family 1, subfamily B, polypeptide 1 (CYP1B1) and myocilin, trabecular meshwork inducible glucocorticoid response (MYOC) mutations were identified in early-onset glaucoma in humans, whereas mutations in the CYP1B1 and FOXC1 were detected in mice with early-onset glaucoma." (PMID 23401651, 2013). "Since Foxc1 is expressed in the developing embryonic TM, mutations or altered expression of FOXC1 could interfere with normal function of the tissue and lead to increased risk of glaucoma." (PMID 22736943, 2012). "Genetic evidence suggests that other genes near FOXC1 may also be involved in the underlying etiology of iridogoniodysgenesis and other eye abnormalities associated with glaucoma." (PMID 22022403, 2011). "FOXC1 mutations cause a variety of developmental abnormalities in the anterior segment of the eye, and they also induce an elevation in intraocular pressures and early-onset glaucoma." (PMID 17653043, 2007). "Additionally, a zebrafish model has shown that aberrant regulation of retinal ganglion cell (RGC) numbers may contribute to developing PCG and early-onset glaucoma due to FOXC1 mutations." (PMID 38671671, 2024). "Further studies of these regions in human patients are likely to explain additional cases of Axenfeld–Rieger syndrome, aniridia, Peters anomaly, and glaucoma, and may possibly contribute to the extreme variability in phenotypes caused by FOXC1 heterozygous variants." (PMID 36284357, 2022). "Manipulation of either foxc1a or foxo1a resulted in aberrant responses to increased oxidative stress and increased cell death in the eye, indicating that impaired response to oxidative stress could also be a key facet of glaucoma development due to loss of FOXC1." (PMID 34576164, 2021).
glaucoma (continued). "Mutations in the Forkhead Box C1 (FOXC1) are known to cause autosomal dominant hereditary Axenfeld-Rieger syndrome, which is a genetic disorder characterized by ocular and systemic features including glaucoma, variable dental defects, craniofacial dysmorphism and hearing loss." (PMID 34809627, 2021). "Furthermore, in some affected family members with glaucoma as a result of FOXC1 mutations, the anterior segment malformation may be very subtle, and easily missed in clinical examination, a feature more in keeping with POAG." (PMID 22736943, 2012). "Taking aniridia as an example, whilst PAX6 mutations remain the predominant cause, variants in CYP1B1, FOXC1, PXDN and SOX11 have also been reported in patients with childhood glaucoma and aniridia." (PMID 41011222, 2025). "Numerous genes and genetic changes have been described in association with childhood glaucoma, with the most common being CYP1B1, MYOC, and FOXC1." (PMID 38386645, 2024). "Approximately 50% of individuals with ARS develop glaucoma, highlighting the significance of FOXC1 in glaucoma pathogenesis." (PMID 38671671, 2024). "In 8 (33%) children with childhood glaucoma one of the following congenital glaucoma associated genes (CYP1B1, FOXC1, LTBP2 and TEK) was confirmed by the genetic examination." (PMID 35144644, 2022). "Heterozygous loss of FOXC1 in humans results in Axenfeld–Rieger syndrome (ARS), which results in increased risk for glaucoma and variable systemic anomalies including defects in craniofacial bone development." (PMID 35885890, 2022). "It is reported that more than 50% patients with FOXC1-related ARS will develop into glaucoma eventually and the median onset age of glaucoma diagnosis is 6 ± 13.0 years." (PMID 34809627, 2021). "The present work reveals that FOXC1 is an important regulator of exocytosis and establishes a new link between FOXC1 and MYOC-associated glaucoma." (PMID 28575017, 2017). "The new connection between MYOC and FOXC1 can improve our understanding of the role of FOXC1 in glaucoma pathogenesis." (PMID 28575017, 2017). "The new connection to MYOC and exocytosis indicates FOXC1’s involvement in additional mechanisms related to glaucoma and further elucidates the mechanisms through which FOXC1 is involved in neurodevelopment and function." (PMID 28575017, 2017). "Mutations in a variety of genes associated with early-onset glaucoma, including MYOC, CYP1BI, FOXC1, PITX2, PAX6, and OPTN, typically disrupt normal development of the trabecular outflow pathway." (PMID 28210622, 2017). "FOXC1 dosage is crucial since mutations that decrease FOXC1 activity below 80%, and FOXC1 duplications that increase FOXC1 copies to 150% both lead to ARS, with elevated IOP and glaucoma pathogenesis." (PMID 28575017, 2017). "Overall, FOXC1 regulation of RAB3GAP opens new directions for FOXC1 involvement in glaucoma pathogenesis through regulations of exocytosis, endocytosis and autophagy." (PMID 28575017, 2017). "By maintaining programmed cell death and thus proliferation of TM cells, FOXC1 is a major player in the onset of glaucoma once deregulated." (PMID 28979898, 2017). "The involvement of FOXC1 in disorders with ocular and neurodevelopmental malformations and in the neurodegenerative disease glaucoma illustrates its importance in neural and ocular development and neuronal health." (PMID 28575017, 2017). "As both, FOXC1 and MYOC, are central genes in early-onset glaucoma pathogenesis we examined the interaction between these two genes, by looking at the effect of FOXC1 on exogenous MYOC secretion." (PMID 28575017, 2017). "In this respect, mutations in FOXC1, PITX2, SH3PXD2B and LMX1B, among others, cause various ASDs and have a significantly increased risk of early onset glaucoma." (PMID 27483349, 2016). "Exclusion of pathogenic variations in known glaucoma genes as CYP1B1, MYOC, FOXC1, PITX2 and PAX6 was additionally done per Sanger sequencing and Multiple Ligation-dependent Probe Amplification (MLPA) analysis." (PMID 27484908, 2016).
glaucoma (continued). "The role of FOXC1 in this type of glaucoma was investigated in twelve Spanish probands via nucleotide variation screening of its proximal promoter and unique exon." (PMID 25786029, 2015). "Further, only 18% of patients with glaucoma and either FOXC1 or PITX2 genetic defects respond to medical or surgical treatment." (PMID 23687430, 2013). "FOXC1 (forkhead box C1) and PITX2 (paired-like homeodomain 2), genes associated with glaucoma-related Axenfeld-Rieger syndrome, were also identified in three of the studies." (PMID 22312193, 2012). "The essential role of these developmental glaucoma genes for the development of the anterior segment and in the development of TM implies that FOXC1, TGFβ2, and BMP4 are crucial for the normal development of drainage structures and preservation of normal IOP." (PMID 22736943, 2012). "Only 18% of patients with glaucoma and either FOXC1 or PITX2 genetic defects responded to medical or surgical treatment." (PMID 17653043, 2007). "However, FOXC1 dysfunction contributes to the death of cells in the trabecular meshwork of the eye, an important step in the development of glaucoma." (PMID 40136424, 2025). "Testing for FOXC1 could be helpful to prevent misdiagnosis and to exclude cases related to secondary congenital glaucoma as the clinical features of Axenfeld–Rieger anomaly/syndrome could be subtle." (PMID 40427049, 2025). "Increased FOXC1 expression due to gene duplication has been shown to result in anterior segment defects, including iris hypoplasia with glaucoma, microcornea, and Peters anomaly, similar to the ocular features described here in the individual with a de novo RARB c.157+1895G>A variant." (PMID 39450403, 2024). "For PAX6 and FOXC1, this is consistent with their broad expression patterns in the eye and the phenotypic heterogeneity and overlap linked to FOXC1 and PAX6 mutations, e.g., iris and corneal defects and higher prevalence of glaucoma, reinforcing a common regulatory network shared by the 2 TFs." (PMID 37856539, 2023). "Interestingly, mutations within PITX2, which physically interacts with FOXC1 and FOXC2, have previously been linked to the ocular conditions Axenfeld-Rieger syndrome and glaucoma." (PMID 36868229, 2023). "Specific to FOXC1, a GWAS study discovered a SNP at ~ 61.7 kb 5′ of FOXC1 (rs2745572[A]) that was significantly associated with primary open-angle glaucoma (POAG) and vertical cup-to-disk ratio, an important endophenotype for glaucoma." (PMID 36284357, 2022). "From 21 glaucoma disease-associated genes with measurable expression, 2 were upregulated (MYOC and FOXE3) and five were downregulated (SH3PXD2B, NF1, SBF2, ADAMTS17, and FOXC1)." (PMID 35348588, 2022). "In 33% of children with glaucoma mutations in the CYP1B1, FOXC1, LTBP2 and TEK genes were found." (PMID 35144644, 2022). "Nearly 50% of children develop glaucoma, and several more recent studies have demonstrated that glaucoma occurs in 20–74% of patient subjects with PITX2 pathogenic variants and 44–100% of patient subjects with FOXC1 pathogenic variants." (PMID 34573386, 2021). "Like FOXC1, mutation of PITX2 results in ARS with early onset glaucoma in many patients." (PMID 34576164, 2021). "GAS7 may interact with other genes implicated in glaucoma pathogenesis such as MYOC, OPTN, WDR36, CAV1, nitric oxide synthase 2 (NOS2), forkhead box C1 (FOXC1), apolipoprotein E (APOE), amyloid precursor protein (APP), and clusterin (CLU)." (PMID 32545285, 2020). "This novel interaction shows an additional role for FOXC1 in later onset glaucoma." (PMID 28575017, 2017). "Exocytosis in glaucoma is involved in glutamate excitotoxicity, ATP secretion, and potentially MYOC secretion, indicating novel pathogenic mechanisms through which FOXC1 might promote glaucoma." (PMID 28575017, 2017). "Based on these facts, we explored the role of FOXC1 in dominant glaucoma." (PMID 25786029, 2015).